CD14 (CD14 molecule)
Diseases named in the same sentence as CD14 in open-access papers (continued):
Sharing a sentence is not in itself a finding about the gene and the disease.
psoriasis (38 papers, 2007 to 2025). An autoimmune condition characterized by red, well-delineated plaques with silvery scales that are usually on the extensor surfaces and scalp. "The presence of CD86+ CD14+ CD16+ cells in psoriasis lesions is linked to increased keratinocyte proliferation." (PMID 38399624, 2024). "In psoriasis, the dysregulation of DNase I in CD14+ cells associated with the incomplete degradation of the DNA in the epidermis that caused parakeratosis has been assumed to play a role in the etiology of parakeratosis through the incomplete degradation of DNA in the epidermis." (PMID 39409000, 2024). "Additionally, both CISH and CLU were found upregulated in I) CD4+ TCM and CD4+ TEM and II) CD14+ monocytes, respectively, which are associated with IL-1β-induced and synovial inflammation, and increased levels have been related to psoriasis and arthritis." (PMID 40084238, 2024). "In unstimulated samples, psoriasis patients displayed a higher proportion of BDCA-4+CD14+ cells compared to healthy donors." (PMID 41303461, 2025). "Analysis of BDCA-4 surface expression within the BDCA-4+CD14+ population showed consistently lower fluorescence intensity in psoriasis patients compared to healthy donors in both unstimulated and activated samples." (PMID 41303461, 2025). "We found a positive correlation between VDR expression on CD3+ lymphocytes and CD14+ monocytes in patients with psoriasis at baseline." (PMID 39409006, 2024). "VDR expression on CD14+ monocytes was higher in patients with psoriasis compared to healthy controls at baseline (p = 0.015)." (PMID 39409006, 2024). "This underlines the need for further investigation of the nuanced involvement of monocyte CD14-related phenotypes in psoriasis and the immunomodulatory modalities involved." (PMID 38558803, 2024). "On the other hand, we found a positive correlation between VDR expression on CD3+ lymphocytes and CD14+ monocytes in patients with psoriasis before the treatment’s start, which ceased to be significant after 24 weeks of the Etanercept treatment." (PMID 39409006, 2024). "Patients with moderate to severe psoriasis had higher VDR expression on CD14+ cells compared to healthy controls." (PMID 39409006, 2024). "In this prospective observational study, we observed a significant difference in VDR expression on CD14+ monocytes when comparing patients with psoriasis and healthy controls at baseline, with a higher expression in the psoriasis group." (PMID 39409006, 2024). "In the present study, we observed great individual variations in VDR expression (%) on both CD3+ and CD14+ cells among patients with psoriasis and in healthy controls, both at baseline and after 24 weeks." (PMID 39409006, 2024). "Evidence of leukocyte activation (GO:0045321, GO:0001775, in CD14+ monocytes) supports the significant role of innate immunity in PsA and psoriasis, possibly contributing to the recruitment of additional immune cells to the inflammatory site." (PMID 40084238, 2024). "Compared with healthy individuals, patients with psoriasis had increased serum levels of soluble CD14 (sCD14) and calprotectin, which are markers of inflammation." (PMID 38689088, 2024). "There was a significant positive correlation between VDR expression on CD3+ lymphocytes and CD14+ monocytes in patients with psoriasis at baseline (p = 0.0005)." (PMID 39409006, 2024). "We observed higher expression of the VDR on CD14+ monocytes in psoriasis patients compared to healthy controls at baseline." (PMID 39409006, 2024). "Immunofluorescence staining of CD14+HLA-DR- M-MDSCs in the inflamed skin of patients with psoriasis revealed that the infiltration of M-MDSCs in psoriatic skin tissue increased significantly compared to that in healthy controls." (PMID 36969174, 2023). "Flow cytometry confirmed that the number of human M-MDSCs (CD11b+CD14+HLA-DR-) was considerably higher in the peripheral blood of patients with psoriasis (P = 0.0065)." (PMID 36969174, 2023).
psoriasis (continued). "Previous studies have also reported an association between HERVs and psoriasis, and the members of the HERV-W family have been found to activate the immune system via CD14/TLR4 signalling and promote the development of a Th1 type of immune response." (PMID 38069048, 2023). "In order to probe the expression of SIRT3 in T cells and monocyes, we isolated CD3+ T cells and CD14+ monocytes from PBMCs of 10 patients with psoriasis and age- and sex-matched healthy volunteers via flow cytometry cell sorting technology." (PMID 37275851, 2023). "Consistent with other studies, we also found an increased number of peripheral blood CD11b+CD14+HLA-DR−/low MDSCs in patients with psoriasis compared to healthy controls." (PMID 36969174, 2023). "To confirm the mechanism by which CaMK4 inhibits IL-10 production through the Erk1/2 and p38 pathways found in mouse macrophages, we sorted peripheral CD14+ monocytes from patients with psoriasis." (PMID 35869084, 2022). "A recent study integrating flow cytometry and scRNA‐seq with published skin data sets examined the Mφ and DC landscape in AD and psoriasis and identified IL‐1B and IL‐23 producing CD14+ DC3s as potential inflammatory modulators in psoriasis." (PMID 35196402, 2022). "Consistent with other studies, we found increased circulating CD14+HLA-DR−/low Mo-MDSCs among CD14+ cells in psoriasis patients when compared to healthy controls." (PMID 32382290, 2020). "We observed that CAV-1 level in psoriasis patients was apparently reduced in peripheral blood mononuclear cells (PBMCs) and it was prominent in CD14+ monocytes." (PMID 30644419, 2019). "CD14+ pathways significantly impacted by IFX in psoriasis were proliferation of immune cells, apoptosis and cell death, and maturation." (PMID 25333715, 2014). "Following culture with GM-CSF, IL-4 and TGF-β, CD14+ monocytes derived from both healthy controls and patients with psoriasis acquired a DC-like phenotype, with CD14 expression decreasing to negligible levels in both groups." (PMID 21933242, 2012). "CD14+ monocytes isolated from both patients with psoriasis and healthy control volunteers were cultured in a cytokine cocktail for 5 days to promote their differentiation into mLCs, then stimulated for 24 h with TNF-α, IL-1β (both 100 ng/mL) or medium alone." (PMID 21933242, 2012). "PsA and psoriasis (Ps) subjects had a higher percentage of circulating inflammatory CD14+CD16+ cells than healthy controls (HC)." (PMID 20102624, 2010). "Interestingly, in vitro stimulation of psoriasis PBMCs markedly reduced—or even completely eliminated—the BDCA-4+CD14+ population." (PMID 41303461, 2025). "However, unlike the previous investigations, the current study discovered that monocyte CD14 had a protective impact against psoriasis." (PMID 38558803, 2024). "There is significant evidence suggesting that CD14 contributes to the pathogenesis of autoimmune conditions, which is also supported by its elevated levels in patients with vasculitis, systemic sclerosis, and psoriasis." (PMID 39409006, 2024). "This aligns with our results showing higher VDR expression on CD14+ cells in patients with psoriasis compared to healthy controls, indicating that disease severity and inflammation might impact VDR expression." (PMID 39409006, 2024). "However, CaMK4 expression was higher in CD14+ monocytes from both patients with psoriasis and healthy controls than in T cell subsets." (PMID 35869084, 2022). "That indicates the percentage of DR3+ CD8+ and DR3+ CD14+ cells might be a novel biomarker in evaluating the severity of psoriasis." (PMID 34354596, 2021). "These function were enriched in CD14+ cells in PsA and CD14+ and CD14- cells in psoriasis patients." (PMID 33303908, 2020).
psoriasis (continued). "The frequency of HLA-DR−/low cells among CD14+ cells of psoriasis patients with BS syndrome was significantly higher when compared with healthy controls (p < 0.001, Mann–Whitney nonparametric U test) and the BH syndrome group (p < 0.001, Mann–Whitney nonparametric U test)." (PMID 32382290, 2020). "Furthermore, multiple experimental investigations have demonstrated that monocyte CD14 expression is much higher in psoriasis patients, which might be attributed to inflammatory mediators in psoriasis patients’ skin tissues driving monocyte CD14 expression." (PMID 38558803, 2024). "A study revealed that Mo-MDSC (CD14+HLA-DR−/low) fractions were elevated in psoriasis patient peripheral blood mononuclear cells (PBMCs) compared to healthy controls, and, importantly, regulatory T cells induced by psoriasis Mo-MDSCs displayed decreased suppressive functionality." (PMID 32382290, 2020). "In PBMCs from psoriasis patients, we analyzed both BDCA-4+CD14+ cells and BDCA-4+CD14− cells, the latter defined as pDCs." (PMID 41303461, 2025). "In peripheral blood of patients with psoriasis, elevated levels of CD14+CD16+ intermediate monocytes and reduced levels of CD14+CD16- classical monocytes have been observed." (PMID 37744329, 2023). "Finally, we also compared the expression of NLRP3 pathway components in the CD14+ monocyte population from psoriatic and healthy individuals, since inflammatory cytokines produced in excess by circulating monocytes also play an important pathological role in psoriasis." (PMID 36293012, 2022). "Taken together, our data provides evidence that the percentage of CD14+HLA-DR−/low MDSC/ CD14+ cells and TNF-α and FOXP3 mRNA expression levels in PBMCs are potential biomarkers for making a distinction between the psoriasis TCM BS syndrome and BH syndrome." (PMID 32382290, 2020). "Furthermore, immunohistochemistry showed abundant numbers of CD11b+, CD11c+, CD14+, CD163+ and plasmacytoid dendritic cells in early‐phase new‐onset psoriasis." (PMID 40181552, 2025). "Interestingly, in psoriasis patients, BDCA-4+CD14+ cells were present at a higher proportion even in unstimulated samples." (PMID 41303461, 2025). "Treatment with Etanercept did not alter VDR expression on CD3+ and CD14+ cells in patients with psoriasis over the 24-week period (p = 0.99, p = 0.96)." (PMID 39409006, 2024). "The Etanercept treatment improved the disease but did not alter VDR expression on CD3+ lymphocytes and CD14+ monocytes in patients with psoriasis." (PMID 39409006, 2024). "Given that the fraction of CD14+HLA-DR−/low MDSC among CD14+ cells positively correlated with psoriatic BS syndrome, we examined the relationship between the fraction of CD14+HLA-DR−/low MDSC and disease severity, as assessed by the psoriasis area and severity index (PASI) score." (PMID 32382290, 2020). "We found lower IL-10 mRNA levels in PBMCs of psoriasis patients when compared to healthy controls, especially in psoriatic BS syndrome patients, in disagreement with the elevated fraction of CD14+HLA-DR−/low MDSC/ CD14+ cells." (PMID 32382290, 2020). "The RNA from circulatory CD14+ monocytes was isolated from PsA patients, psoriasis patients without arthritis (PsO), and healthy controls (HCs)." (PMID 32560314, 2020). "Candidate miRNAs related to monocyte activation (miR-146a-5p, miR-146b-5p and miR-155-5p) were measured in circulatory CD14+ monocytes collected from 34 PsA patients, 17 psoriasis without arthritis (PsO) patients, and 34 normal controls (NCs)." (PMID 30658492, 2019). "In contrast to untreated psoriasis, the infiltrate was relatively T cell poor, with scant neutrophil elastase staining, and few CD14+ cells (not shown)." (PMID 17324275, 2007). "Importantly, BDCA-4 expression remained stable on pDCs, and as demonstrated, combining BDCA-4 with CD14 staining facilitated the accurate discrimination of pDCs from non-pDCs even in psoriasis samples." (PMID 41303461, 2025).
psoriasis (continued). "We found that the proportion of CaMK4+ cells and the mean fluorescence intensity (MFI) of CaMK4 were both higher in peripheral T cell subsets (CD4+, CD8+, and double-negative (DN) cells) and CD14+ monocytes from patients with psoriasis than in those from healthy controls." (PMID 35869084, 2022). "Upregulation of TNF-α expression is in line with the increased fraction of CD14+HLA-DR−/low MDSC/ CD14+ cells seen in psoriatic BS syndrome patients, suggesting that elevated Mo-MDSCs in patients with psoriasis may be involved in the suppression of T-cell activity." (PMID 32382290, 2020). "The histological differences between these papules and psoriasis are that in the papular lesions there are reduced T cells, neutrophils, CD14+ cells, lack of organized dermal T cell and dendritic cell aggregates, and the epidermal reaction has less acanthosis and psoriasiform rete elongation." (PMID 17324275, 2007). "Treatment with Etanercept for 24 weeks did not alter VDR expression on CD3+ and CD14+ cells in this cohort of patients with psoriasis with sufficient serum vitamin D levels at the treatment’s start, implying that VDR expression might not be related to disease severity or the grade of inflammation." (PMID 39409006, 2024). "While there is a minor population of CD14+ DCs in normal skin that has been proposed to drive Th2 responses, the identity and role of CD14+ in psoriasis has not been specifically studied, and CD14+ cells may be a heterogeneous population of either myeloid DCs or macrophages." (PMID 22348003, 2012). "The surface markers of DMSCs derived from both psoriasis and healthy individual were positive for CD105, CD29, CD44, CD73 and CD90 and negative for CD45, CD34 and CD14." (PMID 36065978, 2022). "Furthermore, we found that CD14+ monocytes, but not CD3+ T cells predominantly expressed annexin II in PBMC of patients with psoriasis." (PMID 21311769, 2011).
glioma (36 papers, 2010 to 2025). A benign or malignant brain and spinal cord tumor that arises from glial cells (astrocytes, oligodendrocytes, ependymal cells). "All together, these observations indicate that increased glioma grading is associated with a rise in CD14+ cells expressing activated STAT3 and PD-L1, suggesting their potential use as blood biomarkers." (PMID 35069595, 2021). "Transwell assays were used to evaluate chemotaxis of CD14+ monocytes towards the CM of glioma cells." (PMID 38370418, 2024). "CD45hiCD64+CD14+ peripheral monocytes/MDMs were the next most abundant population, accounting for 32% of leukocytes in glioma, compared with 4% monocytes in PBMCs and 5% macrophages in epileptic brain, consistent with peripheral myeloid infiltration in GBMs." (PMID 37192001, 2023). "In conclusion, these results show the presence of different profiles of glioma patient monocytes depending on CD14, CD16 and SLAN expression." (PMID 36768201, 2023). "While MDSCs are known to inhibit CD8+ T cell proliferation, this study described an inverse association between CD14+ monocytes expressing VNN2 and glioma patient’s tumor grade potentially highlighting a role for VNN2 in less aggressive tumors." (PMID 36428698, 2022). "The data shown in our study indicate that overexpressed JMJD1C increases the expression of M1 markers (IL‐1β, TNF, CXCL9, IL‐23, ROS1, IL‐12a, and IL‐12b) both in the glioma mouse models and in the CD14+ monocytes co‐cultured with glioma cells." (PMID 34586733, 2021). "In all glioma patients, we observed a positive correlation of percentage of CD14+ TREM-1+ cells with the IL-6/IL-10 ratio (P = 0.007) and a negative correlation with the plasma levels of IL-10 (P < 0.0001)." (PMID 32684831, 2020). "Very interesting was the finding of a positive correlation of the level of HMGB1 in glioma patients with percentage of CD14+ TREM-2+ Mo (P = 0.007)." (PMID 32684831, 2020). "We cultured healthy donor monocytes in hypoxic conditions in either serum-free fresh media or glioma-conditioned media and analyzed by flow cytometry for CD11b, CD14, CD15, and HLA-DR expression patterns." (PMID 28666020, 2017). "We found that addition of anti-MIF blocking antibody blocks the formation of CD14+/HLA-DR- MDSC’s induced by glioma-conditioned media in our model system." (PMID 28666020, 2017). "In this study, we developed a novel model to reliably generate human MDSCs from healthy-donor CD14+ monocytes by culture in human glioma-conditioned media." (PMID 28666020, 2017). "Significantly increased CD14+/ HLA-DR- MDSCs were seen for all three monocyte donors cultured under both normoxia and hypoxia in glioma-conditioned media." (PMID 28666020, 2017). "Isolated CD14+ cells were then converted to dendritic cells (DCs), primed with glioma cell lysate and used to sensitize T-cells." (PMID 20195476, 2010). "However, microglia also appear to be present in wtIDH glioma and are more activated than those found in mIDH glioma based on CD14 and CD64 expression." (PMID 36186781, 2022). "In PBMCs culture, glioma-derived exosomes directly promoted IL-10 and arginase-1 production and downregulation of HLA-DR by unstimulated CD14+ monocytic cells, that displayed an immunophenotype resembling that of monocytic myeloid-derived suppressor cells (Mo-MDSCs)." (PMID 28107450, 2017). "However, CD14+ monocytes cultured in glioma-conditioned media show a marked increase in CD14+/HLA-DR- MDSCs." (PMID 28666020, 2017). "However, α-MSH was also reported to fail to prevent NF-κB activation in a glioma cell line, where its inhibitory effects were instead explained by a reduction in the LPS co-receptor CD14." (PMID 27359332, 2016). "Interestingly, another group identified significantly greater percentage of TIM-3 positivity on peripheral CD14+ monocytes from glioma patients versus healthy donors and glioma patients with higher percentage of TIM-3 positivity on CD14+ monocytes having a higher risk for tumor recurrence or death." (PMID 40072074, 2025).